CTNND2 (catenin delta 2)
Description:
Has a critical role in neuronal development, particularly in the formation and/or maintenance of dendritic spines and synapses. Involved in the regulation of Wnt signaling. It probably acts on beta-catenin turnover, facilitating beta-catenin interaction with GSK3B, phosphorylation, ubiquitination and degradation (By similarity). Functions as a transcriptional activator when bound to ZBTB33 (By similarity). May be involved in neuronal cell adhesion and tissue morphogenesis and integrity by regulating adhesion molecules.
Synonyms: NPRAP; GT24
Tractability: Antibody: its Gene Ontology location is reachable by antibodies, with medium confidence. PROTAC: ubiquitination databases record sites on it; its protein half-life has been measured.
Gene: Protein-coding gene on chromosome 5 (10,971,836 to 11,904,446, reverse strand). Ensembl gene ENSG00000169862.
Subcellular location: Nucleus; Cell junction, adherens junction; Cell projection, dendrite; Perikaryon
Subcellular location (Human Protein Atlas): Cell Junctions; Nucleoplasm; Cytosol
Gene Ontology:
Molecular function: beta-catenin binding; protein binding; cadherin binding
Biological process: dendritic spine morphogenesis; regulation of canonical Wnt signaling pathway; synapse organization; cell adhesion; cell-cell adhesion; signal transduction
Cellular component: perikaryon; adherens junction; cytoplasm; nucleus; plasma membrane; postsynaptic density; dendrite
Genetic constraint (gnomAD): Loss-of-function variants: 20 observed, 127.53 expected, observed/expected ratio (o/e) 0.16, 90% interval 0.11 to 0.23. The upper end of that interval is the gene's LOEUF score, 0.23, which puts it in group 1 of 6, group 1 being the genes least tolerant of losing a copy. Missense variants: 1,280 observed, 1,551.1 expected, observed/expected ratio (o/e) 0.83, 90% interval 0.79 to 0.86. Synonymous variants: 720 observed, 666.39 expected, observed/expected ratio (o/e) 1.08, 90% interval 1.02 to 1.15.
Homologues: Orthologues: chimpanzee CTNND2 (100% identical), macaque CTNND2 (99% identical), dog CTNND2 (97% identical), pig CTNND2 (97% identical), rat Ctnnd2 (97% identical), mouse Ctnnd2 (97% identical), tropical clawed frog ctnnd2 (90% identical), guinea pig CTNND2 (84% identical), zebrafish ctnnd2a (78% identical), zebrafish ctnnd2b (77% identical), rabbit CTNND2 (76% identical). Paralogues in human: PKP4 (50% identical), ARVCF (31% identical), CTNND1 (28% identical), PKP2 (19% identical), PKP3 (18% identical), PKP1 (17% identical).
Diseases named in the same sentence as CTNND2 in open-access papers:
CTNND2 is named in the same sentence as 54 diseases in open-access papers, as found by Europe PMC text mining. Sharing a sentence is not in itself a finding about the gene and the disease. The quoted sentences say what the papers report.
autism (16 papers, 2011 to 2025). Persistent deficits in social interaction and communication and interaction as well as a markedly restricted repertoire of activity and interest as well as repetitive patterns of behavior. "Genetic variants of CTNND2 have been associated with attention-deficit/hyperactivity disorder, autism, and myopia." (PMID 39995975, 2025). "Studies in mice have shown that loss of CTNND2 results in decreased learning ability and autism-like behaviors such as reduced sociability and increased anxiety." (PMID 37465584, 2023). "Heterozygous loss of CTNND2 has been linked to a wide spectrum of neurodevelopmental disorders such as autism, schizophrenia, and intellectual disability." (PMID 37465584, 2023). "Hub genes of the turquoise module included one GABA receptor encoding genes such as Gabrb1, one glutamate receptor gene (Grid2) and genes tightly associated with synaptic development and autism (Nrxn1, Lrfn5, Plcb1, Erc2, Frmpd4, Tanc2, Ctnnd2, Dmd)." (PMID 34021132, 2021). "We report here that δ-catenin, which is encoded by CTNND2, an autism candidate gene, directly interacts with the Ank domain of Shank3 at postsynaptic sites through its Armadillo-repeat domain." (PMID 33115499, 2020). "CTNND2 has been implicated as an autism candidate gene, as several deletions and unbalanced translocations have been reported in individuals with autism and other neurodevelopmental disorders." (PMID 33115499, 2020). "Recently, a new gene encoding the adhesive junction-associated delta-catenin protein (CTNND2) has been identified as responsible for manifestation of the symptoms from genetic analysis of female subjects with severe autism." (PMID 27355350, 2016). "Heterozygous variants in CTNND2, encoding the brain-specific protein δ-catenin, are associated with a broad spectrum of neurodevelopmental disorders, including dyslexia, attention deficit hyperactivity disorder, intellectual disability, and autism." (PMID 41502569, 2025). "Genetic variation in CTNND2 has been reported to be involved in neuroplastic processes in the olfactory pathways of rats and is associated with human neurodevelopmental phenotypes, such as autism and intellectual disability." (PMID 39275286, 2024). "In addition, we had a great interest in the observed dendritic spines density and synaptic protein levels in the PFC, one of the major brain regions associated with autism, in Ctnnd2 KO mice." (PMID 37226399, 2023). "Therefore we focused further on δ-catenin as mutations in the coding CTNND2 gene have been observed in a few autism cases." (PMID 33115499, 2020). "In addition, mutations in CTNND2, a gene that plays a key role in neuronal development, particularly in the formation and maintenance of dendritic spines and synapses, have also been recently associated to autism." (PMID 28427329, 2017). "This study defines the clinical symptoms of CTNND2-related neurodevelopmental disorders, outlining a recognizable yet variable phenotype that overlaps with other forms of intellectual disability and autism." (PMID 41502569, 2025). "Next, we find that some of these phenotypes in WT and Ctnnd2 KO mice were also influenced by chronic sleep restriction, which is similarly to that seen in human with autism." (PMID 37226399, 2023). "Overall, results of the present study may have implications for the role of disrupted sleep in patients with CTNND2 gene‐related autism and the evolution of neurodevelopmental disorders." (PMID 37226399, 2023).
autism (continued). "We hypothesized that chronic sleep restriction (SR) would further exacerbate the autism‐like behaviors, cognition, and growth of dendritic spines and synapses in Ctnnd2 KO mice." (PMID 37226399, 2023). "Furthermore, we found that some of these phenotypes in WT and Ctnnd2 KO mice were also influenced by chronic SR, similarly to that observed in humans with autism." (PMID 37226399, 2023). "In short, our study provides a further understanding of the role of disrupted sleep in Ctnnd2 gene deletion induced autism on the evolution of neurodevelopmental disorders in mice, which may be consistently with patients with mutations in CTNND2 gene." (PMID 37226399, 2023). "Interestingly, many of the up-regulated genes are involved in mental conditions and higher cognitive functions, including the schizophrenia- and autism-associated gene SYN2 and cognition- and intelligence-associated genes FMN2, CTNND2, and CACNA1A 67–71." (PMID 36788214, 2023). "The CTNND2 gene coding for δ-catenin is also an autism candidate gene." (PMID 33115499, 2020). "For example, CTNND2 plays a critical role in neuronal development since it has been observed that it is likely rate-limiting for dendritic morphogenesis and maintenance, and its haploinsufficiency is common in autism." (PMID 31208038, 2019). "Interestingly, CTNND2 dysregulation has been reported in several cases of autism and intellectually disabled patients presenting with behavioral problems and dysmorphic features, involving changes in autophagy signaling and arborization of the developing dendrites." (PMID 38637827, 2024). "Accordingly, we had generated Ctnnd2 KO mice using CRISPR‐Cas9 technology and demonstrated that the model animals exhibited autism‐like behaviors, and impaired learning and memory function." (PMID 37226399, 2023). "Collectively, these data suggested that the effects of SR on autism‐like behaviors in WT and Ctnnd2 KO mice were not the same." (PMID 37226399, 2023). "Therefore, our results demonstrated that SR influenced the social novel preference, but not sociability in mice, and deteriorated part of the autism‐like behaviors in Ctnnd2 KO mice." (PMID 37226399, 2023). "Thus, the correct induction of CTNND2 expression through the reduction of REST and TRIM28 may be crucial for normal neuronal development and the prevention of autism, and TRIM28 may be involved in the regulation of CTNND2 by acting as a corepressor of REST." (PMID 27976729, 2016).
Intellectual disability (9 papers, 2006 to 2025). "DYNLRB1 was found to be associated to neuronal survival, INPP5K was found to be associated to cognitive impairment, ZFHX2 was found to be associated to behavioral abnormalities and CTNND2 was found to be associated to mental retardation and intellectual disability." (PMID 33510859, 2021). "Two genes, Semaphorin F (SEMAF) and δ-catenin (CTNND2), which have been mapped to the "critical regions", are potentially involved in cerebral development and their deletion may be associated with mental retardation in CdCS patients." (PMID 16953888, 2006). "This study defines CTNND2-related neurodevelopmental disorders as a clinically variable condition characterized by intellectual disability and behavioral abnormalities." (PMID 41502569, 2025). "Intragenic CTNND2 deletion was detected using molecular karyotyping in two patients with isolated intellectual disability." (PMID 37226399, 2023). "Previous studies have reported that CTNND2 is a candidate gene for intellectual disability, ASD, and growth retardation of dendritic spines and synapses." (PMID 37226399, 2023). "Moreover, CTNND2 is usually deleted in individuals with cri‐du‐chat syndrome, a disorder classically defined by intellectual disability." (PMID 37226399, 2023). "Intragenic CTNND2 deletion is found in patients with isolated intellectual disability." (PMID 30864639, 2019).
Cri-du-chat syndrome (8 papers, 2011 to 2025). Monosomy 5p, also known as Cri du chat syndrome, is a rare autosomal deletion syndrome characterized by a mewing cry (cri du chat) in infancy, multiple congenital anomalies, intellectual disability, microcephaly, and facial dysmorphism. "The human δ-catenin gene (CTNND2) is located on chromosome 5p15.2 where a deletion causes the cri-du-chat syndrome (CDCS), a syndrome with severe cognitive and language impairments, motor delays, and behavioural problems." (PMID 33115499, 2020). "It was previously reported that this gene is located in a region on the short arm of chromosome 5, and hemizygosity of CTNND2 is associated with cri du chat syndrome." (PMID 32586281, 2020). "Interestingly, loss of CTNND2 in humans is associated with the “Cri du chat” syndrome, wherein affected babies may develop breathing problems at birth and require respiratory treatments." (PMID 30728831, 2018). "Among these, there are a number of biomedically relevant genes, such as PAK2 affected by 3q29 microdeletion, CTNND2 affected in Cri-du-Chat syndrome, or MAPT affected by 17q21.31 microdeletion (inset)." (PMID 37164484, 2023). "For fetus 20, SNP array analysis revealed a 32 Mb deletion at 5p15.33p13.3 (involving CTNND2 and DOCK8) which caused cri-du-chat syndrome, and a 21 Mb duplication at 9p24.3p21.3 (involving KANK1) leading to 9p duplication syndrome." (PMID 33674646, 2021). "Supporting a neural-specific role for this protein, its gene, CTNND2, maps to a critical region on chromosome 5p15.2 that is deleted in cri du chat syndrome (CDCS)." (PMID 22022388, 2011). "Targeting of the enhancer located 112 kb upstream yielded upregulation of CTNND2 specifically in the two Cri-du-chat syndrome iPSC lines, but not HEK293T cells (1.8-fold, q = 9e-5; 2.1-fold, q = 2e-7)." (PMID 41278953, 2025).
myopia (8 papers, 2011 to 2025). "CHRM3 and TGFβ1 have been implicated in the pathogenesis of myopia in Taiwanese individuals, while a high-myopia GWAS of Asian datasets identified the SNP rs6885224 in the CTNND2 gene on chromosome 5p15.2 as being associated with myopia." (PMID 39062192, 2024). "CTNND2 is significantly associated with myopia in an Asian GWAS and RBFOX1 has been associated with myopia in a multi-ethnic cohort and also in a Chinese population-based study." (PMID 27623284, 2016). "In another GWAS on Asian cohorts, the gene CTNND2 was found to be highly associated with high myopia." (PMID 23649821, 2013). "CTNND2 is known to be associated with myopia and myopia can influence glaucoma risk." (PMID 27623284, 2016). "Since CTNND2 expression is regulated by Pax6, and that the distribution of Pax6 and δ-catenin/catenin δ2 is remarkably similar, the collaboration of PAX6 and CTNND2 might be associated with myopia." (PMID 23213273, 2012). "However, although the C allele of CTNND2 single nucleotide polymorphism (SNP) rs6885224 was a risk allele for high myopia in our study, the replication study showed this allele was protective against high myopia." (PMID 23213273, 2012). "A later GWAS among Singaporean Chinese subjects found that two single nucleotide polymorphisms (SNPs), rs12716080 and rs6885224 in CTNND2 near MYP16, showed significant associations with high myopia." (PMID 35327754, 2022). "Lastly, the rs6885224 SNP at the CTNND2 gene on chromosome 5p15.2 was identified from a high myopia GWAS of several Asian datasets." (PMID 35327754, 2022). "Our interaction analysis showed at least two genes (CTNND2 and RBFOX1) that have been previously associated with myopia, and are also associated with glaucoma in our datasets." (PMID 27623284, 2016). "In our replication study, we found that neither rs6885224 in the CTNND2 gene nor rs634990 in the 15q14 region was associated with high myopia in the Tujia and Miao populations in Enshi Tujia and Miao Autonomous Prefecture." (PMID 32586281, 2020). "Others have speculated that CTNND2 may regulate the structure and function of the sclera by breaking down E-cadherins in scleral fibroblasts, which may lead to myopia." (PMID 32586281, 2020). "Since the expression of the catenin δ2 protein is regulated by transcription factor Pax6 and PAX6 is another myopia-susceptibility gene, PAX6 and CTNND2 might cooperatively affect myopia development." (PMID 23213273, 2012). "The A allele for rs644242 is protective for high and extreme myopia, and the collaboration of PAX6 and CTNND2 might be associated with the development of this condition." (PMID 23213273, 2012).
prostate carcinoma (6 papers, 2010 to 2024). A carcinoma that arises from epithelial cells of the prostate gland. "CTNND2 genomic amplification and genetic changes have also been reported in cervical cancer 20 and prostate cancer 46, respectively." (PMID 25154973, 2015). "The 5p15.2 region hosts the potential target gene, delta catenin (CTNND2), over-expressed in prostate cancer." (PMID 22174799, 2011).
schizophrenia (6 papers, 2011 to 2023). A major psychotic disorder characterized by abnormalities in the perception or expression of reality. "All these genes are associated with psychiatric conditions, ranging from ID i.e., CNKSR2, CTNNB1, ANK3, CASK and ASD i.e., CTNND2, ANK3 to schizophrenia i.e., CNKSR2 (GWAS, PGC-SCZ 2014) and bipolar disorder ANK3." (PMID 28713243, 2017).
Anxiety (5 papers, 2017 to 2025). Intense feelings of nervousness, tension, or panic often arise in response to interpersonal stresses. "A role for Ctnnd2 in anxiety in mice is supported by altered behaviour of Ctnnd2-knockout mice in contextual fear conditioning paradigms and an association between CTNND2 and anxiety has been found in humans too." (PMID 28381599, 2017). "In addition, overexpression of δ‐catenin, encoded by Ctnnd2, in mice could improve object recognition and social interaction, and reduce anxiety." (PMID 37226399, 2023). "Elevating Ctnnd2 expression in mice resulted in heightened sociability and decreased anxiety while homozygous Ctnnd2 knockout mice exhibited spatial learning deficits and aberrant fear conditioning." (PMID 41502569, 2025). "Conversely, overexpression of CTNND2 in mice resulted in increased sociability and reduced anxiety." (PMID 37465584, 2023). "Ctnnd2 therefore seems to contribute to anxiety in multiple species (rats, mice, humans)." (PMID 28381599, 2017). "In addition, SR deteriorated the self‐restrictive behaviors of Ctnnd2 KO mice in the open‐field test but had no influence on exploration ability and anxiety." (PMID 37226399, 2023).
Cognitive impairment (5 papers, 2020 to 2025). Abnormal cognition is characterized by deficits in thinking, reasoning, or remembering. "Based on previous research, we investigated that Ctnnd2 gene deletion in mice lead to ASD‐like behaviors and cognitive defects." (PMID 37226399, 2023).
breast carcinoma (3 papers, 2021 to 2024). "Predictions of known cancer driver genes in new cancer types include SPTA1, CHD4 and ASXL1 in colorectal cancer, FOXO3, MUC16 and ZFPM1 in breast cancers and CNTNAP2, CTNND2 and TRRAP in lung adenocarcinoma." (PMID 38890488, 2024). "The explanation for our results where there was no conversion in EMT character may be that CTNND2 is independent from EMT in breast cancer or that cells needed a longer time after transfection." (PMID 35879960, 2022).
cervical cancer (3 papers, 2015 to 2020). A primary or metastatic malignant neoplasm involving the cervix. "Like CTNND2 and DAP, MIR365–2 has also been linked to breast and cervical cancers." (PMID 33225922, 2020).
lung carcinoma (3 papers, 2020 to 2024). "successfully deleted a panel of oncogenes in lung cancers, including those encoding for epidermal growth factor receptor (EGFR), CD38, focal adhesion kinase (FAK), NESTIN, remodeling and spacing factor 1 (RSF1), and catenin delta 2 (CTNND2)." (PMID 37356052, 2023).
Alzheimer disease (2 papers, 2011 to 2013). A progressive, neurodegenerative disease characterized by loss of function and death of nerve cells in several areas of the brain leading to loss of cognitive function such as memory and language. "SNP rs6894869 was significantly associated with lipid particle size phenotype BMED and mapped to an intron of CTNND2, which functions in the same pathway as cadherins, plays a crucial role in CNS development and is a partner of the Alzheimer disease-associated gene presenilin-1." (PMID 23628382, 2013).
autism spectrum disorder (2 papers, 2019 to 2022). A spectrum of developmental disorders that includes autism, and Asperger syndrome. "In this sense, theloss of a copy of CTNND2 in CdCs may be associated withintellectual disability, reading problems, learningdifficulties, and autism spectrum disorder (ASD)." (PMID 30985858, 2019).
depression (2 papers, 2021 to 2022). "The correlation of Adcy9, Apc, Camk2b, Camk2g, and Ctnnd2 with the pathological mechanisms of depression was first reported in the present work." (PMID 34520625, 2021).
dyslexia (2 papers, 2018 to 2025). A learning disorder characterized by an impairment in processing written words. "Three CNVs were identified in genes that have been associated with dyslexia (CTNND2, NRCAM, and CNTNAP2) and their role in bone is currently unknown." (PMID 30042735, 2018).